DHODH (dihydroorotate dehydrogenase (quinone))
Diseases named in the same sentence as DHODH in open-access papers (continued):
Sharing a sentence is not in itself a finding about the gene and the disease.
gastric cancer (4 papers, 2019 to 2025). A primary or metastatic malignant neoplasm involving the stomach. "Previous studies have reported that DHODH is upregulated in gastric cancer and that its overexpression is associated with chemoresistance and enhanced malignant behavior of gastric cancer cells." (PMID 40917841, 2025). "The key enzymes involved in up-regulating pyrimidine synthesis, CAD and DHODH, are implicated in enhancing the chemoresistance of gastric cancer by accelerating glycolysis." (PMID 38728242, 2024). "In conclusion, our results suggest that CIRT may induce ferroptosis and modulate macrophage polarization through DHODH-associated pathways in gastric cancer cells." (PMID 40917841, 2025). "The present study found that CIRT decreased the viability, migration, and invasion capabilities of gastric cancer cells, suppressed DHODH expression and ferroptosis resistance, and promoted M1 macrophage polarization." (PMID 40917841, 2025). "This study demonstrated that CIRT promotes ferroptosis and induces M1 macrophage polarization in gastric cancer cells, potentially through the downregulation of DHODH." (PMID 40917841, 2025). "In gastric cancer, the upregulation of DHODH has been shown to contribute to chemoresistance by enhancing glycolysis." (PMID 40917841, 2025). "In vitro, CIRT suppressed DHODH expression and enhanced intracellular iron and reactive oxygen species (ROS) accumulation, promoting ferroptosis in gastric cancer cells." (PMID 40917841, 2025). "These in vivo results further proved that CIRT induced ferroptosis and M1 macrophage polarization to inhibit the development of gastric cancer by downregulating DHODH expression." (PMID 40917841, 2025). "This study aims to elucidate a specific mechanistic pathway by which CIRT modulates ferroptosis and macrophage polarization via DHODH inhibition in gastric cancer." (PMID 40917841, 2025). "In contrast, a high level of DHODH was only observed in patients of gastric cancer with a short overall survival time." (PMID 30643150, 2019). "Furthermore, these effects of CIRT on gastric cancer cells and macrophage polarization were mediated through the downregulation of DHODH." (PMID 40917841, 2025). "Furthermore, downregulation of DHODH attenuates stemness and ferroptosis resistance in gastric cancer cells." (PMID 40917841, 2025). "Similarly, the present study further confirmed that DHODH upregulation promotes the viability, migration, and invasion of gastric cancer cells." (PMID 40917841, 2025). "This study aims to investigate whether CIRT inhibits gastric cancer progression via the regulation of DHODH." (PMID 40917841, 2025). "Targeting DHODH may enhance the therapeutic efficacy of CIRT in gastric cancer." (PMID 40917841, 2025). "DHODH is consistently overexpressed in gastric cancer tissues, and its elevated expression attenuates the tumor-suppressive effects of polymerase theta on the malignant phenotype of gastric cancer cells, suggesting that DHODH may play a promotive role in tumor progression." (PMID 40917841, 2025). "The WB results of ferroptosis key protein showed that compared with GES1 and MC, there were no significant changes in FSP1 and DHODH in gastric cancer cells (Hgc27 and MKN45), slight changes in GPX4, no significant changes in SLC7A11." (PMID 39991579, 2025). "Notably, DHODH overexpression reversed these effects and abrogated the ferroptosis-inducing role of CIRT, indicating that CIRT promotes ferroptosis in gastric cancer cells through DHODH downregulation." (PMID 40917841, 2025). "Notably, the ferroptosis inducer erastin restored M1 polarization despite DHODH overexpression, indicating that CIRT drives M1 macrophage polarization in gastric cancer by downregulating DHODH." (PMID 40917841, 2025).
influenza (4 papers, 2020 to 2025). An acute viral infection of the respiratory tract, occurring in isolated cases, in epidemics, or in pandemics; it is caused by serologically different strains of viruses (influenzaviruses) designated A, B, and C, has a 3-day incubation period, and usually lasts for 3 to 10 days. "DHODH inhibitors demonstrated potent anti-influenza activity through disruption of host pyrimidine biosynthesis, thereby suppressing viral replication." (PMID 41011283, 2025). "For the case of severe influenza A virus infections in mice, a recent report indicated an additive or even synergistic effect for combination treatments using DHODH inhibitors with influenza DAAs." (PMID 33291455, 2020). "Similarly, DHODH inhibition by IMU-838 reduced CD4+ T cell responses to flu antigens." (PMID 40706797, 2025).
lung carcinoma (4 papers, 2020 to 2023). "Though related researches are not numerous, it seems to be a meaningful start for the future application of DHODH inhibitor in lung cancer therapy." (PMID 33971967, 2021). "It is manifested that lung cancer cell lines show higher DHODH expression than normal lung cells and DHODH knockout exerts significant effects on lung cancer cell proliferation inhibition, suggesting that lung cancer cell lines are sensitive to DHODH inhibitors." (PMID 33971967, 2021). "For example, CAD, CTPS, and DHODH had no prognostic effect in LUAD dataset but associated with the clinical outcomes in lung cancer patients derived from GEO datasets." (PMID 32638267, 2020). "Functional studies identified pyrimidine metabolic rate–limiting enzymes DHODH and DTYMK as therapeutic targets in lung cancer." (PMID 32638267, 2020).
Lupus (4 papers, 2020 to 2025). "Additional immune modulatory effects of vidofludimus including decreased inflammation in the lung were demonstrated in a mouse model of systemic lupus erythematosus, findings that are consistent with previous reports on other DHODH inhibitors." (PMID 33291455, 2020). "Subsequently, multiple research teams independently reported that DHODH inhibitor Vi has therapeutic effects on various diseases, including systemic lupus erythematosus, inflammatory bowel disease, renal transplantation rejection reaction, and relapsing–remitting multiple sclerosis." (PMID 38124181, 2023).
psoriatic arthritis (4 papers, 2023 to 2025). Joint inflammation associated with psoriasis. "We performed further studies on DHODH because DHODH inhibitors have shown clinical efficacy for the treatment of rheumatoid and psoriatic arthritis." (PMID 40961924, 2025). "Leflunomide is an immunomodulatory drug used medically to treat rheumatoid and psoriatic arthritis via inhibiting the enzyme dihydroorotate dehydrogenase (DHODH)." (PMID 40892740, 2025).
Arthritis (3 papers, 2017 to 2025). Inflammation of a joint. "DUP785 (Brequinar) and leflunomide have been shown to be potent anticancer and arthritis treatment agents that interfere with DHODH by binding to the narrow region in the hydrophobic tunnel motif of the enzyme that leads to the flavin mononucleotide-ubiquinone redox site." (PMID 40250560, 2025). "GSK-3β inhibitor TDZD-8 treatment suppresses spinal Bax and DHODH mediated mitochondrial ROS levels, inhibits NF-κB mediated NLRP3 inflammation activation, and alleviates arthritis pain." (PMID 37058473, 2023). "Taking into account that LAP shows a great ability to inhibit DHODH in vitro, we hypothesized that LAP could have a therapeutic potential in the context of arthritis by interfering with T-cell proliferation." (PMID 28270195, 2017).
autoimmune (3 papers, 2022 to 2024). "Although our findings did not reveal any overt negative effects of BRQ on the CD8+ T cell response in the context of our preclinical cancer models, DHODH inhibitors are being used clinically in the context of autoimmune disorders to dampen autoimmune T cell activity." (PMID 36453551, 2022).
colon cancer (3 papers, 2014 to 2023). "In this paper, we have demonstrated that impairment of the DHODH function and,as a consequence, of de novo pyrimidine biosynthesis inducesapoptosis in human colon cancer cells upon inhibition of MRC complex III." (PMID 24772329, 2014).
skin cancer (3 papers, 2019 to 2021). "Altogether, our results suggest that DHODH can be targeted for both skin tumor prevention and curative combination therapy." (PMID 31551419, 2019). "Of note, DHODH activity is roughly twice higher in skin cancers than normal skin." (PMID 33971967, 2021). "Using a multistage model of UVB radiation-induced skin cancer, we show that UVB-induced DHODH upregulation is mainly regulated transcriptionally by STAT3." (PMID 31551419, 2019). "Although DHODH 5’UTR mutations have never been reported before in any cancer, it was shown very recently that DHODH plays a key role in the carcinogenesis of SCC and other UV radiation-induced skin cancers and facilitates the development of precancerous skin lesions." (PMID 34900699, 2021). "Recently, a study shows that DHODH, playing a critical role in UVB-induced energy metabolism reprogramming, is upregulated mainly resulting from transcriptional activation by signal transducer and activator of transcription 3 (STAT3) in a multistage model of UVB radiation-induced skin cancer." (PMID 33971967, 2021). "Indeed, despite manifesting hyperkeratosis, mice treated with an inhibitor of DHODH developed neither actinic keratosis nor skin tumors following exposure to chronic UVB irradiation." (PMID 31551419, 2019). "DHODH is not well studied in cancer, but it has recently been demonstrated that it plays an important role in the carcinogenesis of SCC and other UV radiation-induced skin cancers." (PMID 34900699, 2021).
small cell lung carcinoma (3 papers, 2020 to 2025). Small cell lung cancer (SCLC) is a highly aggressive malignant neoplasm, accounting for 10-15% of lung cancer cases, characterized byrapid growth, and early metastasis. "For example, silencing of DHODH or DHODH inhibition by high-dose BQ sensitized the small cell lung cancer U1690 cell line to TRAIL-induced apoptosis." (PMID 40738904, 2025). "DHODH has been studied in several diseases including oral squamous cell carcinoma and small cell lung cancer." (PMID 36672495, 2023).
brain cancer (2 papers, 2025). A primary or metastatic malignant neoplasm affecting the brain. "Elevated DHODH expression in colorectal, hepatocellular, breast, renal, and brain cancers correlates with poor prognosis, therapy resistance, and immune evasion." (PMID 41369379, 2025). "Overall, these results corroborate recent studies that point to the potential therapeutic benefits of DHODH inhibition in brain cancer." (PMID 40325182, 2025).
childhood cancer (2 papers, 2021 to 2024). "Targeting pyrimidine ribonucleotide synthesis, specifically by inhibiting the enzyme dihydroorotate dehydrogenase (DHODH), has recently shown promising preclinical results in different types of cancers including pediatric cancers." (PMID 38332874, 2024). "Inhibitors of the enzyme dihydroorotate dehydrogenase (DHODH), which is involved in the de novo pyrimidine ribonucleotide synthesis pathway, have proven to be effective in preclinical trials against several cancers including pediatric cancers." (PMID 38332874, 2024). "Here we report that the pyrimidine biosynthetic enzyme dihydroorotate dehydrogenase (DHODH) is an attractive therapeutic target for MYCN-amplified neuroblastoma, a childhood cancer with poor prognosis." (PMID 34462431, 2021).
chronic myeloid leukemia (2 papers, 2019 to 2020). "Very recently, two other newly developed DHODH inhibitors for AML and one for chronic myeloid leukemia (CML) have been described." (PMID 31319822, 2019).
depression (2 papers, 2021 to 2023). "Thus, DHODH may be associated with depression via neuroinflammation." (PMID 33504850, 2021).
diabetes (2 papers, 2021 to 2025). "Further analysis using this model for obesity-induced diabetes revealed that DHODH inhibitors delay pancreatic β cell death and improve metabolic balance." (PMID 34113829, 2021).
Dravet syndrome (2 papers, 2022 to 2024). "Namely, we showed that DHODH inhibition by TERI negatively regulates CA1 MFR set points and suppresses CA1 hyperexcitability in a genetic model of Dravet syndrome, one of the most intractable and severe forms of childhood epilepsy." (PMID 35045289, 2022).
endometrial cancer (2 papers, 2023 to 2026). Primary or metastatic malignant neoplasm involving the endometrium (mucous membrane that lines the endometrial cavity). "BCOR mutations are also enriched in salivary gland and endometrial cancers, extending DHODH inhibitors’ potential beyond AML." (PMID 41549155, 2026). "An in vitro experiment demonstrated that the inhibition of DHODH in endometrial cancer cell lines significantly induced replication-associated DNA damage and hindered replication fork progression." (PMID 38136273, 2023). "Overall, the data shown in this work demonstrates that endometrial cancer patients with tumors exhibiting higher DHODH expression levels are significantly associated with histologic high-grade tumors." (PMID 38136273, 2023). "Furthermore, endometrial cancer patients who exhibited DHODH overexpression had a higher risk of high-grade tumors." (PMID 38136273, 2023). "To correlate our findings with human endometrial cancer, we quantified the expression data of DHODH in endometrial cancer using the TCGA database." (PMID 38136273, 2023). "We analyzed 507 patients from the Pan Cancer endometrial cancer dataset and observed that 38% of those patients overexpressed DHODH mRNA in tumor tissue samples relative to normal endometrial tissue." (PMID 38136273, 2023). "Our results demonstrate that the inhibition of DHODH in endometrial cancer cells leads to a decrease in cellular proliferation, which is in line with other works." (PMID 38136273, 2023). "In the future, physiological or pathological circumstances of targeting DHODH in endometrial cancer have to be determined in vivo." (PMID 38136273, 2023). "We targeted one of the dysregulated genes (DHODH) that is critical for metabolism of nucleotide biosynthesis in endometrial cancer cell." (PMID 38136273, 2023). "Our data show that the number of endometrial cancer cell nuclei stained with γH2AX and co-localized with 53BP1 were significantly increased in DHODH inhibitor-treated cells versus untreated cells, HEC-1B: 31% versus 1.3% (** p < 0.01) and AN3CA: 52% versus 32% (*** p < 0.001), respectively." (PMID 38136273, 2023). "Interestingly, our in vitro data show that the inhibition of DHODH impairs DNA replication stability and promotes delayed DNA fork progression in endometrial cancer." (PMID 38136273, 2023). "Here, we tested whether treatment with a PARP1 inhibitor (Olaparib) in combination with a DHODH inhibitor (teriflunomide) synergized to increase DSBs in endometrial cancer cells." (PMID 38136273, 2023). "Whether DHODH represents a viable target for endometrial cancer treatments in vivo needs to be determined." (PMID 38136273, 2023). "Furthermore, endometrial cancer cells were sensitive to the DHODH inhibitor either alone or in combination with the Poly (ADP-ribose) polymerase 1 inhibitor." (PMID 38136273, 2023). "Given the prevalence of DHODH overexpression in endometrial tumors, it may have a significant impact on developing targeted endometrial cancer treatment or influencing treatment response." (PMID 38136273, 2023). "In addition, our data also strongly suggest that inhibiting DHODH alone and in combination with the PARP1 inhibitor promotes replication-associated genomic instability and significantly decreases the survival of endometrial cancer cells." (PMID 38136273, 2023). "To assess the possible deregulation of DHODH in endometrial cancer patients due to genomic alteration, we first analyzed whether DHODH expression levels were associated with mutation load or aneuploidy in tumors of endometrial cancer patients obtained from The Cancer Genome Atlas (TCGA) database." (PMID 38136273, 2023). "In addition, the high level of DHODH expression in combination with other endometrial molecular signatures is likely used for patient stratification as well as the identification of subtypes of endometrial cancer." (PMID 38136273, 2023).
endothelial dysfunction (2 papers, 2024). In vascular diseases, endothelial dysfunction is a systemic pathological state of the endothelium (the inner lining of blood vessels) and can be broadly defined as an imbalance between vasodilating and vasoconstricting substances produced by (or acting on) the endothelium. "The mechanism studies showed that leflunomide and its active metabolite teriflunomide decreased lipid accumulation and improved endothelial dysfunction via the DHODH/AMPK signaling pathway." (PMID 39113703, 2024). "Taken together, these data indicate that leflunomide and teriflunomide attenuate endothelial dysfunction and exert a vascular protective effect via regulating the DHODH/AMPK/eNOS pathway." (PMID 39113703, 2024).
epilepsy (2 papers, 2019 to 2024). A brain disorder characterized by episodes of abnormally increased neuronal discharge resulting in transient episodes of sensory or motor neurological dysfunction, or psychic dysfunction. "Using state-of-the-art optical, electrophysiological, and metabolic tools, we identified mitochondria as a central regulator of firing rate set points in hippocampal circuits and DHODH inhibition as a novel strategy to treat epilepsy." (PMID 31047779, 2019). "Altogether, these results demonstrate that cerebral DHODH inhibition conveys potent antiepileptic protection even in the severe, pharmacoresistant genetic model of epilepsy." (PMID 31047779, 2019). "Our results highlight the potential of cerebral DHODH as a therapeutic target for epilepsy." (PMID 31047779, 2019). "Given that DHODH is the leading computation prediction of the metabolic modeling analysis based on hippocampal transcriptome of epilepsy patients and rodent epilepsy models, we asked whether i.c.v. injection of TERI regulates the susceptibility of mice to seizures." (PMID 31047779, 2019).
esophageal SCC (2 papers, 2020 to 2021). "Here, we revealed one intriguing potential mechanism that DHODH modulated β-catenin signaling in esophageal squamous cell carcinoma (ESCC)." (PMID 33060568, 2020). "In addition, it was found that in esophageal SCC, elevated DHODH levels promote cell proliferation by stabilizing β-catenin." (PMID 34900699, 2021).
mesothelioma (2 papers, 2024 to 2025). A usually malignant and aggressive neoplasm of the mesothelium which is often associated with exposure to asbestos. "Indeed, we observed that H2052 mesothelioma cells carrying NF2 mutations, exhibited higher levels of CAD and DHODH compared to normal cells and other PM cell lines with wild-type NF2." (PMID 40707702, 2025). "Given that mesothelioma is poorly vascularized, resulting in limited glucose availability in situ, we further assessed the sensitivity to DHODH inhibitors under glucose-limited conditions." (PMID 40707702, 2025). "Moreover, both commercial mesothelioma cell lines and primary patient-derived cells (PDCLs) with inherent NF2 deficiency exhibited greater sensitivity to DHODH inhibition compared to NF2-intact counterparts (I and EV4J–M)." (PMID 40707702, 2025). "Analysis of ChIP-Seq data from mesothelioma cell lines indicated that both CAD and DHODH are potential targets of the YAP-TEAD1 transcriptional complex (Fig. EV6E,F)." (PMID 40707702, 2025). "Similarly, in mesothelioma cells with inherent NF2 deletions, DHODH inhibition led to a notable reduction in tumor growth." (PMID 40707702, 2025).